ZNF560 (zinc finger protein 560)
Description:
May be involved in transcriptional regulation.
Synonyms: FLJ31986
Tractability: No criterion of Open Targets' tractability assessment is met for any kind of drug.
Gene: Protein-coding gene on chromosome 19 (9,466,355 to 9,498,616, reverse strand). Ensembl gene ENSG00000198028.
Subcellular location: Nucleus
Subcellular location (Human Protein Atlas): Nucleoplasm; Nuclear speckles
Pathways (Reactome):
Gene expression (Transcription): Generic Transcription Pathway
Gene Ontology:
Molecular function: DNA-binding transcription factor activity, RNA polymerase II-specific; RNA polymerase II transcription regulatory region sequence-specific DNA binding
Biological process: regulation of transcription by RNA polymerase II; regulation of DNA-templated transcription
Cellular component: nucleoplasm; nucleus
Genetic constraint (gnomAD): Loss-of-function variants: 51 observed, 77.18 expected, observed/expected ratio (o/e) 0.66, 90% interval 0.53 to 0.83. The upper end of that interval is the gene's LOEUF score, 0.83, which puts it in group 3 of 6, group 1 being the genes least tolerant of losing a copy. Missense variants: 929 observed, 963.26 expected, observed/expected ratio (o/e) 0.96, 90% interval 0.91 to 1.02. Synonymous variants: 319 observed, 333.7 expected, observed/expected ratio (o/e) 0.96, 90% interval 0.87 to 1.05.
Homologues: Orthologues: chimpanzee ZNF560 (97% identical), macaque ZNF560 (93% identical), mouse Zfp78 (23% identical), Drosophila melanogaster CG3281 (16% identical), Drosophila melanogaster Phs (15% identical), Drosophila melanogaster CG2712 (13% identical). Paralogues in human: ZNF778 (31% identical), ZNF266 (30% identical), ZNF20 (30% identical), ZNF559 (28% identical), ZNF69 (28% identical), ZNF555 (28% identical), ZNF177 (27% identical), ZNF264 (27% identical), ZFP90 (26% identical), ZNF599 (26% identical), ZNF805 (26% identical), ZNF596 (26% identical), and 50 more.
Diseases named in the same sentence as ZNF560 in open-access papers:
ZNF560 is named in the same sentence as 9 diseases in open-access papers, as found by Europe PMC text mining. Sharing a sentence is not in itself a finding about the gene and the disease. The quoted sentences say what the papers report.
colorectal cancer (1 paper, 2018). A primary or metastatic malignant neoplasm that affects the colon or rectum. "The ZNF560 gene has been reported in colorectal cancer studies." (PMID 30419062, 2018).
osteosarcoma (1 paper, 2025). A usually aggressive malignant bone-forming mesenchymal neoplasm, predominantly affecting adolescents and young adults. "Recently, the overexpression of the ZNF560 protein in osteosarcoma has been associated with poor patient prognosis, while its downregulation reduces tumor cell viability and migration and induces apoptosis, indicating its potential as a predictive biomarker for the disease." (PMID 41155227, 2025).
prostate carcinoma (1 paper, 2023). A carcinoma that arises from epithelial cells of the prostate gland. "Moreover, the preferential expression of the hypoxic and castration resistance gene set within the Cases group of the Porto cohort and the identification of ZNF560 in the CPC-Gene cohort demonstrate there is a chronic hypoxia mechanism involved in prostate cancer progression." (PMID 37020039, 2023).
tumor (3 papers, 2013 to 2025). "The transcription level of ZNF728 in the tumor decreases by lessthan two-fold, the level of ZNF560 remains almost unchanged, while the level ofZFP42, on the contrary, increases by 17 times." (PMID 36348719, 2022). "The transcriptionlevel of most of the genes (with the exception of ZNF728, ZNF560, and ZFP42) inthe tumor is reduced by more than three-fold, to values comparable to those inother tissues." (PMID 36348719, 2022).
cancer (2 papers, 2018 to 2025). A tumor composed of atypical neoplastic, often pleomorphic cells that invade other tissues. "Zinc finger protein 560 (ZNF560), a member of the zinc finger protein family, plays crucial roles in various biological processes, including development, differentiation, metabolism, and apoptosis, and is closely associated with different stages of cancer progression." (PMID 40356901, 2025). "Since there is little research on the role of ZNF560 and SETX in cancers, more researches are needed to understand their roles in LUAD." (PMID 30419062, 2018).
ZNF560 also shares sentences with these, for which no sentence is quoted: lung squamous cell carcinoma (1 paper); nodular melanoma (1); small cell lung carcinoma (1); superficial spreading melanoma (1).